PDCD1 (programmed cell death 1)
Diseases named in the same sentence as PDCD1 in open-access papers (continued):
Sharing a sentence is not in itself a finding about the gene and the disease.
tumor (continued). "The anti-programmed cell death 1 (PD-1)/anti-programmed cell death-ligand 1 (PD-L1) immune checkpoint inhibitors (ICIs) block immune checkpoint pathways, activating a tumor specific T cell immune response." (PMID 36456932, 2022). "Both immune checkpoint inhibitor PDCD1 and tumor vaccine are capable of inhibiting M2 formation or promoting its depletion." (PMID 35186730, 2022). "Further analysis of the association between the Tumor Recurrence Factor risk score and common immune checkpoints of tumors showed that the Tumor Recurrence Factor risk score was correlated with CD47, CTLA7, HAVCR2, LAG3, PDCD1, and other immune checkpoints." (PMID 35677036, 2022). "Previous studies showed that PDCD1 (PD1), CD274 (PDL1), and CTLA-4 were closely associated with immune escape in the tumor microenvironment." (PMID 35273591, 2022). "Another characteristic of a hot tumor is the higher activity of checkpoint proteins as well as its more aggressive nature, such as PDCD1, which is another sign of a hot tumor." (PMID 35937987, 2022). "The aim of this study is to uncover processes inhibiting PDCD1/CD274 expression thereby enhancing anti‐tumour immune responses." (PMID 35802807, 2022). "Studies have ascertained that PDCD1 and CD274 expressions in tumor cells and tumor-infiltrating immune cells are associated with improved prognosis, which supports our finding." (PMID 35356506, 2022). "The high correlation of HMOX1 with CD86 and PDCD1 LG2 also suggests that interactions between tumor cell ferroptosis and immune cells need to be studied in more detail." (PMID 34975326, 2022). "Here we used imaging mass cytometry to simultaneously quantify 35 proteins in a spatially resolved manner on tumor tissues from 26 melanoma patients receiving anti-programmed cell death-1 (anti-PD-1) therapy." (PMID 36281356, 2022). "Tumor cells express programmed death ligand 1 (PD-L1), which interacts with the activated T cells that show high expression of programmed cell death 1 (PD-1)." (PMID 36371159, 2022). "We found that the exhausted CD8+ T cells located in the core of the tumor had a higher expression of immune checkpoint molecules, including PDCD1, CTLA4, LAG3, TNFRSF9/CD137, CD27, and HAVCR2." (PMID 34513820, 2021). "Recently, antibodies targeting the programmed cell death-1 (PD-1) pathway have been widely used in numerous combination regimens to improve the tumour response and prolong the overall survival (OS) of HCC patients." (PMID 34733154, 2021). "ZDHHC16 expression was significantly positive associated with clinicopathological stage, tumor grade and ICB immunotherapy key genes (i.e., CD274, CTLA4, HAVCR2 and PDCD1, etc.)." (PMID 33794886, 2021). "In another recent study, a single-cell RNA-sequencing of murine organotypic tumor spheroids undergoing programmed cell death 1 (PD-1) blockade was performed." (PMID 34359827, 2021). "Molecules like programmed cell death-1 (PD-1) ligands (PD-L1 and PD-L2) are upregulated on tumor cells, impeding the activation of PD-1+ effector cells upon ligand-receptor interaction." (PMID 34712668, 2021). "This is partly due to the immunosuppression of the tumor microenvironment, mediated by PDCD1/PD‐ligand 1 (L1) upregulation." (PMID 33513276, 2021). "Programmed cell death 1 (PD-1) expressed on M2 macrophages combining with the programmed cell death ligand 1 (PD-L1) expressed on tumor cells exerted immunosuppressive effect." (PMID 34062992, 2021). "Since deletion of Pdcd1 in the PD-1cKO mice led to variable effects on tumor size, the relationship between the tumor size and phenotype of the TILs was investigated." (PMID 34912335, 2021). "In hypoxia status, tumor cells inhibited immune cells’ antitumor ability by interacting with inhibitory receptors in immune cells like PDCD1, TIGIT, and LILRB or weakening the immune-stimulation ligand–receptor interactions such as CCL, TNF, and FASLG." (PMID 34956900, 2021).
tumor (continued). "PDCD1 was obviously upregulated in ILC2s obtained from PBMCs (P<0.0001) and tumor tissues (P<0.0001) of NSCLC patients compared with ILC2s from HDs." (PMID 34194433, 2021). "Lilrb4 RNA was expressed at an even higher level than Pdcd1, a known inhibitory receptor molecule, which is known to have a prominent role in tumor immunity." (PMID 33974041, 2021). "Other studies on multiple occasions have substantiated the potential of CRISPR/Cas9-mediated disruption of PDCD1 in boosting anti-tumor activities of CTLs and even CD8+ memory CTLs." (PMID 34446084, 2021). "Programmed cell death 1(PD-1)/PD-1 ligand (PD-L1) checkpoint blockade is a promising clinical anticancer treatment modality by blocking the binding of PD-L1 on tumor cells to PD-1 on activated T cells to reactivate T-cell-mediated antitumor immunity." (PMID 33469052, 2021). "Lastly, we demonstrated that the association between NKX2–3 and tumor mutation burden (TMB) and PDCD1 (programmed cell death 1) of PCa." (PMID 33402116, 2021). "Histological staining of the resected tumor showed high expression levels of programmed cell death-ligand 1 (PD-L1) and programmed cell death-1 (PD-1)." (PMID 34722283, 2021). "Similar to the exhaustion markers, expression of PDCD1 was rarely found in C01, C12, or C11, but was uniquely detected in C02 and C06, the percentages of which were decreased with higher expression of tumor PD-L1." (PMID 33754038, 2021). "HAVCR2/TIM-3 and PDCD1 were not only increased with disease progression, but also displayed consistent levels of elevation in MF lesions (plaque and/or tumor) when compared to different controls." (PMID 34204115, 2021). "The important discovery that programmed death ligand 1 (PD-L1) expression on tumor cells inhibits programmed cell death 1 (PD-1) on T cells to escape immune surveillance has opened an era of tumor immunotherapy." (PMID 34429434, 2021). "Noteworthy was the cell intrinsic effect of Pdcd1 deletion on the tumor growth in adult PD-1cKO mice with a twofold reduction in the size of large tumors within a 7-day period, from day 18–25 post-tumor implant." (PMID 34912335, 2021). "PD1 gene (Pdcd1) disruption using CRISPR/Cas9 in anti-CD133 CAR T cells was shown to increase tumor killing in vitro while inhibiting in vivo tumor growth in a orthotopic glioma xenograft model." (PMID 33746981, 2021). "In the PD-1cKO mice, a complete deletion of Pdcd1 in tumor-infiltrating T cells (TILs) after tamoxifen treatment led to the inhibition of tumor growth of both small and large tumors." (PMID 34912335, 2021). "In particular, the use of cytotoxic T lymphocyte antigen 4 (CTLA4), programmed cell death 1 (PD-1), and programmed cell death 1 ligand 1 (PD-L1) inhibitors in the clinic has become a landmark breakthrough in tumor immunotherapy." (PMID 34326876, 2021). "Most CA-CRCs showed a high expression of the immune checkpoint protein PDCD1: 18/31 (58%) when PDCD1-positive lymphocytes in the tumor center were counted and 21/31 (68%) based on PDCD1-positive lymphocytes in the invasive margin." (PMID 34680073, 2021). "The programmed cell death 1 (PD-1) is expressed on activated T cells and programmed cell death ligand 1 (PD-L1) is upregulated on tumor cells possibly by activation of EGFR and PI3K-Akt or JAK/STAT pathways." (PMID 34298761, 2021). "For example, PDL1 expression in CSCs protects from immune attack by braking the activation signaling pathways in anti-tumor effector cells, such as T cells and NK cells, via programmed cell death 1 (PD1) signaling." (PMID 33535613, 2021). "In this paper, we report a case of anti-programmed cell death-1 (PD-1) treated with combined RT once CN reduced the primary tumor burden (TB)." (PMID 34211459, 2021). "Typically, Programmed cell death 1 (PD-1) and its ligand Programmed cell death ligand 1 (PD-L1) mediates tumor immunosuppression by promoting T cell apoptosis and Treg induction." (PMID 34880897, 2021).
tumor (continued). "Since TNBC patients express none of these three receptors (ER, PR, and HER2) exhibit a worse prognosis, making anti-tumor immune system re-identify tumor cells through inhibiting the programmed cell death 1 pathway became a solution that can be tried." (PMID 34778188, 2021). "Meanwhile, the programmed cell death 1 (PD-1) and its ligand (PD-L1) pathway, which inhibits anticancer response, have been investigated in many tumor types." (PMID 33923934, 2021). "Pretreatment sPD-1 level correlated with PDCD1 gene expression in matching tumor tissue (ρ = 0.467, p < 0.001)." (PMID 33499013, 2021). "Immune checkpoint inhibitors targeting programmed cell death 1 (PD-1) activate tumor-specific immunity and have shown remarkable efficacy in the treatment of melanoma." (PMID 33925387, 2021). "T cell-derived EVs containing programmed cell death 1 inhibit tumor cell immune escape by triggering programmed death-ligand1internalization." (PMID 35059436, 2021). "NK cells have been verified to have cytotoxic effects against tumor cells in several cancers, this activity was largely influenced by the expression of the inhibitory molecule programmed cell death 1(PD1)." (PMID 33477833, 2021). "Programmed cell death-1 (PD-1)/PD-L1 ligand 1 (PD-L1) (CD279) is an inhibitory checkpoint, which can inhibit the activation of T and B cells in the tumor microenvironment." (PMID 34948105, 2021). "High expression of exhausted T-cell marker genes supported by established studies, including CXCL13, HAVCR2, and PDCD1, was concentrated in tumor tissue in single-cell transcriptional profiles." (PMID 34434188, 2021). "Interaction between programmed cell death 1 and programmed death ligand 1 (PD-L1) plays an important role in tumor evasion through T cell inactivation." (PMID 33893830, 2021). "Deletion of Pdcd1 in PD-1cKO adult mice led to tumor growth regression and complete responses, comparable to PD-1Ab treatment or PD-1KO mice, except for tumor growth inhibition of large tumors (>1,000 mm3)." (PMID 34912335, 2021). "Although PDCD1 most typically relates to its expression on tumor-infiltrating lymphocytes (TILs), there is increasing evidence of tumor-intrinsic PDCD1 expression." (PMID 34067485, 2021). "Binding of PDCD1-L1 to its corresponding ligand PDCD1 negatively regulates the activity of immune cells and induces the immune evasion of tumor cells." (PMID 34143198, 2021). "Conversely, expression of the genes associated with NK cell exhaustion, such as PDCD1, CTLA4, KLRC1, NR4A1, and SOCS3, was upregulated in tumor-infiltrating NK cells." (PMID 34535671, 2021). "Programmed cell death 1 (PD-1) and programmed death-ligand 1 (PD-L1) inhibitors are representative immunotherapies that prevent the escape mechanism of tumor cells and promote restoration of T cell function." (PMID 35096867, 2021). "Programmed cell death 1 (PD-1) is widely expressed in tumor-infiltrating lymphocytes (TILs) of triple-negative breast cancer (TNBC)." (PMID 34172932, 2021). "Recent meta-analyses of the efficacy of antibodies targeting PDCD1/CD274 as monotherapy found that this treatment is associated with more tumor responses and increased overall survival (OS) compared to conventional therapy." (PMID 34067485, 2021). "In the clinic, immune checkpoint inhibitors (ICIs) targeting programmed cell death 1 (PD-1) and programmed cell death-ligand 1 (PD-L1) exhibit a potent and durable anti-tumor activity in LUAD patients." (PMID 33386920, 2021). "Through the combination of programmed cell death-1 (PD-1) and programmed cell death-ligand 1 (PD-L1), it can promote tumor cells escape from host immune surveillance." (PMID 34297698, 2021). "In the tumor microenvironment, PDCD1 on the surface of immune cells binds to the PDCD1LG1 and PDCD1LG2 receptors on the surface of tumor cells to activate a series of signal factors in immune cells." (PMID 34917126, 2021).
tumor (continued). "Programmed cell death ligand-1 (PD-L1), an immune checkpoint protein highly expressed on the cell surface in various cancer cell types, binds to programmed cell death-1 (PD-1), leading to T-cell dysfunction and tumor survival." (PMID 34577564, 2021). "Programmed cell death -1(PD-1) interacting with its corresponding ligand PD-L1 leads to immune suppression via preventing the T-cell activation in the tumor." (PMID 33562324, 2021). "Prior work has suggested that vaccination can be combined with inhibition of the programmed cell death 1/programmed death ligand 1 (PD-1/PD-L1) axis, cytokine support, and local activation of the innate immune system locally in the tumor." (PMID 34396986, 2021). "Owing to broad and notable clinical anti-tumor activity, anti-programmed cell death-1 (PD-1)/anti-programmed cell death-ligand 1 (PD-L1) antibodies have been indicated for almost all types of cancer, and form a part of the current standard of care." (PMID 34764951, 2021). "For example, some researches have already found that immune biomarkers include programmed cell death-1 (PD-1), infiltration of the CD8+ T-cell, PD ligand 1 (PD-L1) expression, and tumor mutation burden (TMB) for immunotherapy in CRC." (PMID 34868393, 2021). "The programmed cell death ligand-1 (PD-L1) expression of these M2 macrophages clearly has potential for major effects on programmed cell death 1 (PD1) expressing tumor infiltrating T cells." (PMID 34135908, 2021). "Recently, Chen et al12 demonstrated that CD38 upregulation in tumor induces resistance to programmed cell death 1 (PD‐1)/programmed cell death ligand 1 (PD‐L1) blocking antibodies and coinhibition of CD38 and PD‐L1 improves antitumor immune responses." (PMID 31991058, 2020). "The use of monoclonal antibodies (mAbs) to block either programmed cell death 1 (PD-1) or anti-programmed cell death ligand 1 (PD-L1) prevents the downregulation of T cell effector function, allowing T cells to mediate tumor cell death." (PMID 33287455, 2020). "While activated, CD8+T cell induced tumor cell to express some factor to recruit macrophage, which weakened the efficacy of PDCD1 immunotherapy." (PMID 33062410, 2020). "Checkpoint proteins, such as programmed cell death-1 (PD-1) on T lymphocytes and PD-1 ligand (PD-L1) receptors on tumor cells, allow tumor cells to keep the host immune response in check." (PMID 32467761, 2020). "PD-L1 is a glycoprotein, expressed by both cancer cells and stromal immune cells in the tumor, that engages the programmed cell death 1 (PD-1) receptor expressed on the surface of infiltrating cytotoxic T cells (CTLs)." (PMID 34212113, 2020). "For example, checkpoint ligand-receptor pairs, such as tumor Treg CD80-Th17 cell CTLA4 and tumor Treg CD274-Th17 cell PDCD1, were identified in our study." (PMID 33584715, 2020). "In recent years, one major immune checkpoint therapy has involved a monoclonal antibody against programmed cell death-1 (PD-1)/programmed cell death-ligand 1 (PD-L1), which is expressed in a variety of tumor cells and immune cells." (PMID 33336070, 2020). "The programmed cell death 1 (PD-1) receptor on the surface of immune cells interacts with its ligand, programmed cell death ligand 1 (PD-L1), which can be produced by tumor cells or immunosuppressive cells, and suppresses the cytotoxic function of T-cells." (PMID 34968306, 2020). "The use of checkpoint inhibitors, such as nivolumab, atezolizumab, or durvalumab, by regulating the programmed death ligand 1/programmed cell death 1 (PD-L1/PD-1) axis, also enhanced the anti-tumor activity of T-cells to modify tumor microenvironment." (PMID 33212810, 2020). "Currently, EOC clinical trials center upon monoclonal antibodies against the immune checkpoint inhibitor programmed cell death-1 (PD-1), which suppresses the anti-tumor function of CD8 + T cells." (PMID 32444701, 2020).
tumor (continued). "We found the up-regulation of cytotoxic cells, CD274 (PD-L1), PDCD1, CTLA-4, HAVCR2, IFN-γ, and so on in high-risk group, whereas opposite result was observed only in absolute tumor purity." (PMID 32537435, 2020). "Recently, modulation of tumor immunity by the programmed cell death-1 (PD-L1/PD-1) immune checkpoint pathway is identified as an alternate mechanism of immune evasion." (PMID 32093152, 2020). "Checkpoint ligand-receptor pairs (e.g., tumor Treg CD80-Th17 cell CTLA4 and tumor Treg CD274-Th17 cell PDCD1) were identified." (PMID 33584715, 2020). "In the programmed cell death-1 (PD-1) and programmed cell death ligand-1 (PD-L1) pathway, the PD-L1 expressed by tumor or tumor-infiltrating immune cells binds to PD-1, inhibiting T-cell receptor signaling and blocking antitumor immune response." (PMID 31527709, 2020). "Selective deletion of myeloid-specific PD-1 by targeting the Pdcd1 gene effectively suppressed tumor growth in several tumor models by mediating antitumor immunity (enhanced T effector memory cells) despite preserved T cell-specific PD-1 expression." (PMID 32917214, 2020). "Programmed cell death-ligand 1 (PDL1, encoded by CD274) and 2 (PDL2, encoded by PDCD1LG2) are expressed by antigen presenting cells and some tumours, and bind to programmed cell death protein 1 (PD1, encoded by PDCD1) on effector T cells." (PMID 32582553, 2020). "Within the TME, T-cell receptor sensitization and interferon (IFN)-γ secretion make the tumor cell and the antigen-presenting cell express the programmed cell death-1 (PD-1) receptor and its ligand (PD-L1) on their surfaces." (PMID 32691290, 2020). "CD103+ TRM, both in tumor and non-tumor tissue, are marked by expression of PDCD1, ITGAE, CXCR6, and SPRY1 in lung cancer." (PMID 32471032, 2020). "In this study, we analysed the GSE108989 data set of T cells and found that NOTCH1 and FBXW7 mutations in CRC patients were associated with higher expression levels of PDCD1, CTLA4 and GZMB of tumour‐infiltrating CD8+ T cells." (PMID 32924269, 2020). "Immunosuppressive cytokines and inhibitory proteins, such as transforming growth factor-β (TGF-β), interleukin (IL)-4, programmed cell death 1 (PD-1), and programmed death ligand 1 (PD-L1), allow tumor cells to escape immune attack." (PMID 32679922, 2020). "Among the many immune checkpoints, programmed cell death 1 (PD-1) and its ligand programmed cell death ligand 1 (PD-L1) have become the “star molecules” due to their high expression levels in a variety of tumor cells." (PMID 33396754, 2020). "Programmed cell death-1 (PD-1)/programmed cell death-ligand 1 (PD-L1) pathway is one of the most important signaling pathways that mediate tumor immune escape." (PMID 30717285, 2019). "We investigated the immunomodulatory activities of lenvatinib in the tumor microenvironment and its mechanisms of enhanced antitumor activity when combined with a programmed cell death-1 (PD-1) blockade." (PMID 30811474, 2019). "According to recent studies, tumor cells interfere with T-cells through co-inhibitory factors such as programmed cell death 1 and cytotoxic T-lymphocyte antigen 4, and they regulate the immune response, promoting tumor progression." (PMID 30695059, 2019). "LAG3-/-/PDCD1-/- double knockout mice have also shown enhanced clearance of and survival from multiple transplanted tumor types." (PMID 31007846, 2019). "Over the past decade, one of the most remarkable breakthroughs in cancer therapy has been tumor immunotherapy, in particular immune checkpoint inhibitory programmed cell death 1 (PD-1)/programmed cell death ligand 1 (PD-L1) blockade." (PMID 30891423, 2019). "Programmed cell death-1 (PD-1) is an immune-checkpoint receptor expressed by T cells, and programmed cell death ligand-1 and -2 (PD-L1 and PD-L2) are expressed in the tumor microenvironment of various cancers, including genitourinary tumors." (PMID 31533818, 2019).